LEPR (leptin receptor)
Diseases named in the same sentence as LEPR in open-access papers (continued):
Sharing a sentence is not in itself a finding about the gene and the disease.
cancer (continued). "In this meta-analysis, we found statistical evidence for a significant but week association of cancer risk with the LEP G2548A (or A19G) SNP but not with the LEPR Q223R SNP." (PMID 24146750, 2013). "LEPR rs12037879 also presented interaction with family history of cancer." (PMID 23593308, 2013). "Besides, LEPR rs12037879 present more important roles by interaction with smoking status, family history of cancer and LEPR rs6690625 in colorectal carcinogenesis." (PMID 23593308, 2013). "Moreover, LEPR rs12037879 and rs6690625 exhibited more important roles in colorectal carcinogenesis by interaction with smoking status and family history of cancer." (PMID 23593308, 2013). "In this regard, the downstream consequences of LEPR signalling, namely sustained activation of the PI3K–AKT–mTOR pathway, become all the more important because, among human cancers, PI3KCA is among the most commonly mutated genes and a target of emerging anti-cancer therapeutics." (PMID 36450983, 2022). "Two previous meta-analyses indicated that LEPR rs1137101 G>A polymorphism might not be a risk factor for cancer." (PMID 31196966, 2019). "However, several primary studies also suggested that LEPR rs1137101 locus could promote the progression of cancers." (PMID 31196966, 2019). "The results of these meta-analyses indicated that LEPR rs1137101 G>A polymorphism might not be associated with the risk of cancer." (PMID 31196966, 2019). "Besides adipocytes, cancer-associated fibroblasts (CAFs), the principal cellular component of the stroma, also express leptin receptor and secrete leptin, which sustains a short autocrine loop and is able to target tumor epithelial cells enhancing cancer cell growth and invasiveness." (PMID 29188139, 2017). "Potential questions remaining from these studies were related to the role of the leptin receptor in the cancer cells themselves, because xenografted cancer cells maintain functional leptin receptors and the LepDB mice still possess a functional short form of the leptin receptor." (PMID 25919692, 2015). "The identification of Leptin receptor antagonists capable of blocking the effects of Leptin could lead to the development of new therapeutic procedures for the treatment of various types of cancer." (PMID 26034683, 2014). "Another LEPR polymorphism, rs6690625, although did not exert any significant main effect on cancer risk, but showed interactions with smoking status and family history of cancer in colorectal carcinogenesis." (PMID 23593308, 2013). "The leptin receptor (LEPR) is expressed in many tumors, making cancers primed to respond to adipocyte-derived leptin." (PMID 39284708, 2024). "Thus, targeting Leptin-LepR signaling may represent a novel strategy for cancer therapeutics." (PMID 37650871, 2023). "A significant interplay among leptin and IGF-I signaling has been suggested in cancer cells which synergistically increase the activation of EGFR and LEPR and mediate TNBC progression." (PMID 36077676, 2022). "Conversely, the expression levels of LEPR, POMC, MC4R, and NEGR1 in two (GBM and PAAD), two (CHOL and LUSC), four (LUAD, LUSC, PCPG, and THCA), and two (CHOL and PCPG) types of cancer were higher than those of the corresponding normal tissues, respectively." (PMID 33299884, 2020). "Previous literature demonstrated that leptin receptor was found in normal, high-grade PIN lesions and malignant prostatic epithelium, respectively." (PMID 33046976, 2020). "The leptin receptor (LEPR), which is expressed in multiple cancers, stimulates the growth and invasion of activated cancer cells and promotes angiogenesis." (PMID 28399860, 2017). "Leptin is able to bind to the leptin receptor (ObR) and then activates the intracellular JAK/STAT, MAPK/ERK1/2 and PI3K/AKT pathways, promoting cancer progression." (PMID 28415788, 2017).
cancer (continued). "Consequently, a total of 11 studies were enrolled in the meta-analysis investigating the relationships between LEP/LEPR/ADIPOQ/ADIPOR1/ADIPOR2 variants and total PCa risk, and ten studies were included in the pooled-review discussing these polymorphisms' impact on the aggressiveness of cancer." (PMID 27768592, 2016). "Inhibition of leptin STAT3 signaling, achieved by administration of leptin antagonists, by leptin receptor monoclonal antibodies, or by upregulating SOCS3 would facilitate apoptosis and impede cancer cell growth." (PMID 26982332, 2016). "Interestingly, human xenograft models revealed that LEPR expression is essential for the development and maintenance of ALL and different types of cancer." (PMID 41226303, 2025). "This suggests that different cancer cells respond differently to regulation of leptin receptor levels, and that these levels do not necessarily reflect the impact of leptin signaling regarding cancer-related outcomes." (PMID 39609706, 2024). "For cancers such as SCCs that originate from native tissues that do not express LEPR, reports of LEPR expression have relied mostly on immunolabelling with antibodies of unclear specificity." (PMID 36450983, 2022). "Since LEP/LEPR is over-expressed in so many processes, they could not be generally used as cancer markers; however, if specific phenotypic variants of LEPR are involved with cancers, which is yet to be studied, then such phenotypes could be used as cancer markers." (PMID 31592340, 2019). "This study clearly demonstrates twofold higher leptin receptor gene and protein expression in cancer granulosa cell lines compared to non-cancer cell lines." (PMID 28861689, 2017). "Also, while adiponectin receptor expression showed no notable differences between adipose and cancer tissues, leptin receptor was significantly higher in adipose tissue." (PMID 40642843, 2025). "Indeed, upon binding its receptor (LEPR), leptin activates several oncogenic pathways, such as JAK/STAT, MAPK, and PI3K/AKT, and seems to affect cancer immune response by inducing a proinflammatory immune polarization and eventually enhancing T-cell exhaustion." (PMID 36291602, 2022). "It is noted that the relative expression levels of leptin and leptin receptor were not uniformly distributed in the pan-cancer cohort, which provides a basis for the pathological involvement of other leptin receptors in tumors, which requires further exploration." (PMID 29682217, 2018).
metabolic disease (26 papers, 2014 to 2025). A congenital disorder (due to inherited enzyme abnormality) or acquired (due to failure of a metabolically important organ) disorder resulting from an abnormal metabolic process. "To further support a potential benefit of disrupting MCJ in the liver on metabolic disorders, we tested the effect of siMCJ in weight gain in LepRdb mice, which show a continued increased weight due to a genetic mutation in the leptin receptor leading to a deficiency in leptin-mediated signaling." (PMID 32620763, 2020). "In the study carried out by us earlier, it was observed that in AO patients with MS/metabolic disorders carriership of the R223R genotype of the leptin receptor gene was associated with higher BMI and insulin levels; in men it was also associated with larger waist circumference." (PMID 26504811, 2015). "Furthermore, in women with AO and metabolic disorders with the R223R genotype, leptin levels were higher than those in women, carriers of the 223Q allele of the LEPR gene (60.744 ± 5.581 ng/mL and 47.521 ± 3.243 ng/mL, resp.; p = 0.045)." (PMID 26504811, 2015). "Our previous studies found that large yellow tea ameliorated metabolic disorders by reducing lipogenesis and altering microbiota in leptin receptor knockout rats." (PMID 36230016, 2022). "It has been indicated that the levels of leptin and leptin receptor and also LEP rs7799039 and LEPR rs1137101 polymorphisms are associated with metabolic disorders." (PMID 34407095, 2021). "For AO patients evaluated by us with and without metabolic disorders, frequency of the 223R allele of the LEPR gene was low and amounted to 0.438 and 0.410, respectively." (PMID 26504811, 2015). "The study of LepR+ MSCs holds immense promise for advancing our understanding of HSC biology, tissue regeneration, metabolic disorders, and immune responses." (PMID 38891042, 2024). "However, in women with AO with and without MetS/metabolic disorders (general cohort), carriers of the 223R allele of the LEPR gene, leptin levels were higher than those in individuals with the Q223Q genotype (57.124 ± 0.370 ng/mL and 46.301 ± 2.752 ng/mL, resp.; p = 0.030)." (PMID 26504811, 2015).
infection (17 papers, 2011 to 2025). The state of being infected such as from the introduction of a foreign agent such as serum, vaccine, antigenic substance or organism. "In various infection models, leptin receptor deficiency (db/db mice) was shown to reduce neutrophil trafficking to the site of infection." (PMID 33584724, 2020). "Specifically, Bangladeshi children who harbor the DQB1*0601 heterozygous and homozygous haplotypes of HLA, and those with a Q223R substitution in the leptin receptor, are more susceptible to infection with E. histolytica." (PMID 29554130, 2018). "Cohort studies in Bangladesh revealed that polymorphisms in several genes, including those encoding human leukocyte antigen (HLA) and the leptin receptor, are involved in susceptibility to infection with E. histolytica." (PMID 29554130, 2018). "Leptin receptor deficiency impairs TFH generation and antibody responses in immunisation and infection." (PMID 34031386, 2021). "The mRNA levels of both leptin receptor isoforms were decreased upon infection in the stromal vascular fraction of adipose tissue in wild-type mice." (PMID 32709166, 2020). "Our results show that acute infection with N. caninum led to a decrease in the levels of leptin that was also accompanied by decreased leptin receptor expression in adipose tissue." (PMID 32709166, 2020). "Overall, our work shows that N. caninum infection influences leptin production and leptin receptor expression early on in infection." (PMID 32709166, 2020). "LEPR expression was specifically downregulated using siRNA treatment for 48h, then the recombinant human leptin (rLep) was added at 10 ng/mL (normal condition), and 100 ng/mL (hyperleptinemia) for 24 hours before infection." (PMID 40125513, 2025). "Having determined that N. caninum infection influenced leptin mRNA levels, we assessed whether transcription of the leptin receptor could also be influenced by infection." (PMID 32709166, 2020). "Here, we sought to assess whether acute infection with N. caninum infection influenced the production of this adipokine as well as leptin receptor mRNA levels." (PMID 32709166, 2020). "Similarly, the risk of C. difficile infection in humans is higher in LEPR Q223R (rs1137101) model, which is a homozygous allelic mutation that results in impaired STAT3 signaling and increased dissemination of infection." (PMID 29868503, 2018). "Moreover, mice with defective leptin receptor are metabolically challenged and upon infection with T. cruzi suffer high mortality." (PMID 30534129, 2018). "Leptin (LEP) and its receptor (LEPR) participate in the immunological response during infection." (PMID 21943151, 2011). "LEP and LEPR participate in the immunological response during infection." (PMID 21943151, 2011). "However, in their study, leptin receptor (lepr) ablation reduced bacterial burden, suggesting that leptin signaling might play a different role in defense towards infections by different species of microbes." (PMID 35933481, 2022). "The same macrophage specific leptin receptor knockout mice also had elevated pulmonary IL-13 and TNF compared to WT mice 48 h after infection with S. pneumoniae." (PMID 33584724, 2020). "Following infection at 10 dpi, six of the DEGs were immune genes (GAL1, GAL2, GAL7, ABCB1, LEPR and SNED1) and two were involved in NOD-like receptor signaling pathway (K60 and HSP90B1), all were upregulated in expression in line 63 birds." (PMID 31578366, 2019). "Leptin receptor mutant db/db mice also had reduced survival and impaired viral clearance when infected with influenza virus, as well as reduced IFN-γ production in the lungs following infection." (PMID 33584724, 2020). "LEPR mRNA was lowly expressed and did not respond to treatments or to selective breeding toward resistance or sensitivity to infection." (PMID 31514326, 2019).
infection (continued). "Spleens of both the resistant and sensitive lines did not express leptin mRNA and lowly expressed LEPR mRNA, regardless of infection by MDV, while mRNAs of TNF and TNFR1 were induced in the spleens of both sensitive and resistant lines (TNF, 10- and 3-fold; TNFR1, 2- and 1.5-fold, respectively)." (PMID 31514326, 2019). "The mice lacking functional leptin receptor in T cells (LepRT−/−) limits pH1N1 influenza mortality and infection severity in obese mice suggesting that leptin signaling in T cells may be a critical mediator of pH1N1 severity in obese mice." (PMID 30534129, 2018). "Analysis of RNA-seq dataset from spleens of chickens four days after intranasal infection with bursal disease virus (IBDV) showed a significant induction of TNF and TNFR1 (p ≤ 0.05); no induction of TNFR2; and no or low expression of leptin and LEPR (<1 RPKM), respectively." (PMID 31514326, 2019).
cardiovascular disease (14 papers, 2012 to 2025). "A meta-analysis conducted by Wu’s group suggested that LEPR polymorphism was significantly associated with the increased risk of cardiovascular disease." (PMID 37533068, 2023). "Apart from the effect of LEPR on the JAK/STAT pathway, Hou and Luo have suggested a relationship between the leptin, JAK/STAT and mitogen-activated protein kinases (MAPK) signal pathways with an effect on cardiovascular diseases." (PMID 34496773, 2021). "We postulate that the absence of the leptin receptor in the SSLepR mutant rats model produces a level of metabolic and inflammatory stress that overrides sex-based protective mechanisms seen in females vs. males in other cardiovascular disease models." (PMID 41463113, 2025).
genetic disorders (11 papers, 2019 to 2025). "Its use is limited to people who have been diagnosed with one of three specific rare genetic disorders caused by proopiomelanocortin (POMC), proprotein convertase subtilisin/kexin type 1 (PCSK1), or leptin receptor (LEPR) deficiency." (PMID 36297523, 2022).
immune dysfunction (5 papers, 2012 to 2023). "About 3% of obese children have mutations in the leptin (LEP) gene and the leptin receptor (LEPR) and can also present with delayed puberty and immune dysfunction." (PMID 33511092, 2020). "Approximately 3% of obese children exhibit mutations in the leptin (LEP) gene and the leptin receptor (LEPR), which can lead to delayed puberty and immune dysfunction." (PMID 37762850, 2023).
endocrine disorder (4 papers, 2016 to 2024). "In fact, LepR deficiency is an autosomal-recessive endocrine disorder that is currently underdiagnosed because of the lack of access to genetic testing and insufficient recognition." (PMID 37006245, 2023).
bacterial infection (3 papers, 2014 to 2021). "Fourth, leptin (ob/ob) and leptin receptor (db/db) deficient mice showed severe immune abnormalities and greater susceptibility to viral and bacterial infection." (PMID 24722122, 2014). "In leptin receptor-deficient mice, studies showed that STAT3, STAT5, and ERK pathways play a key role in host defence against bacterial infections and in leukocyte function." (PMID 33907162, 2021). "Down-regulation of leptin/leptin receptor was reported to drastically affect cell resistance to amoeba and bacterial infection in several species." (PMID 34544390, 2021).
nervous system diseases (3 papers, 2021 to 2024). "Seven of these proteins have cis-acting pQTLs that colocalise with or are causal for neurological diseases: DDR1, IL12, NEP, CD33, DPEP1, GPNMB, and LEPR." (PMID 34857772, 2021).
adenocarcinoma (2 papers, 2007 to 2017). A common cancer characterized by the presence of malignant glandular cells. "Our data has also shown that leptin/LEPR signaling enhanced proliferation in the HEY3 and SKOV3 adenocarcinoma cell lines also via JAK2/STAT3." (PMID 29212170, 2017).
brain diseases (2 papers, 2024 to 2025). "Of the significant reverse MR relationships, the brain disorders demonstrated associations with the increased expression of six proteins (PAMR1, MAVS, F11R, REN, GER and LEPR) and decreased expression of three proteins (TNFRSF4, BTN2A1, ENPP6)." (PMID 40456753, 2025).
degenerative diseases (2 papers, 2024 to 2025). "IF regulates lipid metabolism primarily via genes including FABP4, WNT10B, PCK1, PLIN1, LEPR, and ADIPOQ, providing energy for cold adaptation, whereas PF positively influences in vivo degenerative diseases mainly through genes such as ATP5F1A, ATP5PO, SDHB, NDUFS8, SDHA, and COX5A." (PMID 40136641, 2025).
heart disease (2 papers, 2012 to 2017). "The threefold effect size is greater than that in other included studies, which assessed the association between the LEPR gene variant and heart disease." (PMID 28368354, 2017).
psychiatric disease (2 papers, 2015 to 2016). "However, after accounting for prenatal tobacco use, the associations between LEPR/cg21655790 methylation and 1) un-medicated psychiatric disease, and 2) poor fetal growth were both still significant." (PMID 26303856, 2015). "In these additional analyses we found that prenatal tobacco use was significantly associated with active psychiatric disease and was non-significantly associated with decreased methylation at LEPR/cg21655790." (PMID 26303856, 2015). "This suggests that decreased placental DNA methylation near the leptin receptor locus (cg21655790) may be involved with the biological processes that result in poor fetal growth in women with active psychiatric disease." (PMID 26303856, 2015). "In sum, even though tobacco use frequently occurs with prenatal psychiatric disease, the links between active psychiatric disease, poor fetal growth, and decreased methylation at the LEPR locus are not explained by prenatal tobacco use." (PMID 26303856, 2015). "A locus near the transcription start site of the leptin receptor (cg21655790) had methylation levels that were decreased in the presence of: 1) SGA/IUGR, and 2) active but not resolved psychiatric disease (among mothers not on antidepressants)." (PMID 26303856, 2015).
haematopoietic diseases (1 paper, 2017). "Because human and mouse CD73+ cells express the leptin receptor, identifying CD73+ cells as an indicator of MSCs may advance understanding of their relationship with HSCs and their use in cell therapy for haematopoietic diseases." (PMID 28684854, 2017).
respiratory disorders (1 paper, 2010). "The presence of the functional leptin receptor in the lung recognizes the potential involvement of leptin in the pathogenesis of respiratory disorders, however, whether it represents a friend or a foe is not yet elucidated." (PMID 21040518, 2010).
LEPR also shares sentences with these, for which no sentence is quoted: hypertriglyceridemia (4 papers); Prader-Willi syndrome (4); prediabetes (4); acute lymphoblastic leukemia (3); Hypoinsulinemia (3); hypothyroidism (3); inflammation (3); LEPR deficiency (3); mood disorder (3); non-small cell lung carcinoma (3); acromegaly (2); cervical cancer (2); Crohn disease (2); endotoxemia (2); essential hypertension (2); glomerulosclerosis (2); hypothalamic hypothyroidism (2); idiopathic scoliosis (2); infectious disease (2); intrauterine growth restriction (2); invasive ductal carcinoma (2); lipid metabolism disorders (2); Nephropathy (2); neuropathy (2); non-alcoholic fatty liver (2); Onset (2); Parkinson’s (2); POMC deficiency (2); retinopathy (2); rheumatoid arthritis (2).
A further 90 diseases each share a sentence with LEPR in 2 papers or fewer.